RAP1B (RAP1B, member of RAS oncogene family)
Diseases named in the same sentence as RAP1B in open-access papers (continued):
Sharing a sentence is not in itself a finding about the gene and the disease.
infection (6 papers, 2020 to 2024). The state of being infected such as from the introduction of a foreign agent such as serum, vaccine, antigenic substance or organism. "In this scenario, the fact that PKA negative regulation on infection was abrogated in the presence of the constitutively active G12V mutation, suggests that Rap1b is required in the phosphorylated and inactive form to completely abolish the cAMP/Epac/Rap1b pathway of infection." (PMID 36897926, 2023). "In accordance with these observations, analyses of RNA-seq data obtained after 24 and 48 h of infection revealed that cardiomyocyte infection caused an increase in gene expression of Epac1 and Rap1b, while Rap1GAP2, a protein that induces inactivation of Rap1b, presented a decreased expression." (PMID 38156015, 2023). "Rap1b is gradually recruited to the cell membrane after infection, peaking at 24 hpi, which is consistent with the Rap1b activation dynamics on the cell membrane and in the cytoplasm." (PMID 37515145, 2023). "Overall, our data suggest that activation and relocalization of Rap1b are required as a mediator of the cAMP/Epac1 pathway during the TCT infection." (PMID 36897926, 2023). "In addition, we found a PKA-dependent inhibition of infection, presumably by phosphorylation of Rap1b, and potentially of Epac." (PMID 36897926, 2023). "The strong contribution of RAS-related protein 1b (Rap1b) to cytoskeleton remodeling determines intracellular and extracellular physiological activities, including the successful infection of viruses in permissive cells, but its role in the HSV-1 life cycle is still unclear." (PMID 37515145, 2023). "In accordance, data collected from pull-down experiments designed to identify only the active form of Rap1b (Rap1b-GTP), and infection assays using cells transfected with a constitutively active mutant of Rap1b (Rap1b-G12V), strongly suggest the participation of Rap1b as mediator of the pathway." (PMID 36897926, 2023). "In this work, we have gathered evidence strongly suggesting that the cAMP/Epac/Rap1b/ERK pathway is activated during the early steps of host cell infection and that it would be negatively regulated by PKA, possibly through the phosphorylation of Epac and/or Rap1b." (PMID 36897926, 2023). "Then we use Brucella wild type (WT) infection the cells after the silencing of Rab9A and RAP1B." (PMID 33489935, 2020). "Therefore, a hypothesis about how Rap1b responds to ICP4 to regulate membrane-involved infection emerged spontaneously; this paper presents evidence for the proposed model on HSV-1-infected human corneal epithelial cells." (PMID 37515145, 2023). "Experimental infection of chickens and cells with an avian HEV isolate from China (CaHEV) led to upregulated expression and activation of Rap1b both in vivo and in vitro." (PMID 35138149, 2022). "The protein expression of RAP1b and PIK3CD was inhibited following infection with N. seriolae." (PMID 39717544, 2024). "Thereupon, Rap1b, CDC42 cascade signaling, and Cofilin, the direct executor of cytoskeleton regulation, are likely to be potential host therapeutic targets for antiviral strategies during the early and lytic infection of HSV-1 in epithelial cells." (PMID 37515145, 2023). "Similar to Rap1b, Rab5, and Rab7 are the GTPases belonging to the Ras GTPase superfamily that broadly control budding, uncoating, motility, and fusion of vesicles in most cell types; however, the role of Rap1b in mammalian HEV (naked form) infection requires further investigation." (PMID 35138149, 2022).
cardiovascular disease (1 paper, 2025). "Mechanistically, Rap1B promotes NO production in response to laminar shear stress and suppresses proinflammatory signaling under disturbed flow, positioning it as a key modulator of endothelial inflammation in cardiovascular disease." (PMID 40508181, 2025).
inflammation (1 paper, 2023). Aberrant reaction of the microcirculation characterized by movement of fluid and leukocytes from the blood into extravascular tissues. "Our previous study showed that long-term exposure to low-dose MC-LR increased chronic colorectal inflammation, fibrosis, and barrier damage through activating the CSF1R/Rap1b signaling pathway." (PMID 37756005, 2023).
RAP1B also shares sentences with these, for which no sentence is quoted: diabetic nephropathy (2 papers); Insulin resistance (2); parasite infection (2); prostate carcinoma (2); age-related macular degeneration (1); B-cell lymphoma (1); Bovine mastitis (1); cardiac hypertrophy (1); central serous retinopathy (1); chronic lymphocyte leukemia (1); COVID-19 (1); degenerative myopia (1); diabetic retinopathy (1); epilepsy (1); esophageal carcinoma (1); eye hemorrhage (1); head and neck cancer (1); hematological disorder (1); intracranial hemorrhage (1); lumbar disc herniation (1); lung (1); macular degeneration (1); mastitis (1); microcephaly (1); myelodysplastic syndrome (1); neuropathic pain (1); neutropenia (1); Oral Cancer (1); osteopetrosis (1); osteoporosis (1).
A further 8 diseases each share a sentence with RAP1B in 1 paper.